TLR4 (toll like receptor 4)
Diseases named in the same sentence as TLR4 in open-access papers (continued):
Sharing a sentence is not in itself a finding about the gene and the disease.
lipid metabolism disorders (14 papers, 2020 to 2026). "The intestinal-flora-disorder-mediated activation of TLR4 signaling pathways aggravates lipid metabolic disorders, further causing liver lipid deposition." (PMID 36079919, 2022). "The inhibition of CYBB in zebrafish embryos leads to lipid metabolism disorders and excessive activation of the TLR4/NF-κB pathway, triggering liver injury and immune-inflammatory responses." (PMID 40692778, 2025). "Yue’s study demonstrated that PKP can improve lipid metabolism disorders by activating peroxisome proliferator-activated receptor gamma (PPARγ) in adipocytes and inhibiting the Toll-like receptor 4/nuclear factor kappa B (TLR4/NFκB) signaling pathway." (PMID 41001671, 2025). "For example, red mold rice significantly reduced cholesterol, LDL, and arterial plaque through TLR2 and TLR4 pathways, while monascin alleviated lipid metabolism disorders by modulating key gene expressions and enhancing beneficial bacterial populations." (PMID 40002095, 2025). "Current studies on PRP in reducing blood lipids primarily highlight its ability to mitigate lipid metabolism disorders by inhibiting the TLR4/NF-κB signaling pathway." (PMID 41001671, 2025). "The enhancement of intestinal barrier function prevents the influx of endotoxins into the liver with the blood, thereby inhibiting the TLR4/NF-κB pathway and mitigating lipid metabolism disorders." (PMID 38004120, 2023). "Furthermore, we discovered that fgl2 combined with TLR4 mediates the activation of the Myd88-dependent signaling pathway, which may contribute to inflammation and lipid metabolism disorders." (PMID 32863955, 2020). "TLR4 is the first discovered member of the TLR family, and it is also a modulator in multiple pathological processes such as lipid metabolism disorders, immune inflammatory reactions, and oxidative stress." (PMID 35156897, 2022). "We found that fgl2 interacted with TLR4 on macrophages and regulated inflammatory signaling pathways and the Nod-like receptor protein 3 (NLRP3) inflammasome, leading to liver damage and lipid metabolism disorders in the progression of NASH." (PMID 32863955, 2020). "Existing studies have proved that inhibiting this pathway can improve lipid metabolism disorders in NAFLD mice and alleviate the inflammatory state of the liver, proving that inhibition of the TLR4/NF-κB signaling pathway is a potential therapeutic approach for NAFLD." (PMID 39730994, 2024).
lupus nephritis (14 papers, 2012 to 2025). Glomerulonephritis in the context of systemic lupus erythematosus. "There are four SLEmetaSig100 genes (NFAIP3, IRAK4, MYD88, TLR4) in NF-kappa B signaling pathway that have been implicated in the pathogenesis of lupus nephritis coupled with upregulation of inflammatory cytokines." (PMID 29975701, 2018). "The pathogenic role of TLR4+ plasma cells in lupus nephritis development is well known." (PMID 35858908, 2022). "Overexpression of TLR4 in mice has led to autoimmune glomerulonephritis and lupus-like disease, suggesting that LPS-mediated TLR4 signaling plays a pivotal role in lupus nephritis." (PMID 21860649, 2012). "Moreover, they establish HMGB1, TLR4, and MYD88 as novel molecular markers for NETs-mediated renal inflammatory damage in lupus nephritis, providing new targets for the prevention, diagnosis, and treatment of this condition." (PMID 41208960, 2025). "Taken together, our data showed that HMGB1 in SLE bone marrow inflammatory microenvironment could promote the senescence of MSCs via TLR4/NF-κB signaling pathway, and inhibiting HMGB1 by EP could improve lupus nephritis and reverse the senescence signs." (PMID 31303606, 2019). "The intense and altered expression of TLR2, TLR4, and RAGE in patients with active LN, however, could reflect a role of these receptors in the development and severity of lupus nephritis." (PMID 22892043, 2012). "In this study, we firstly demonstrated that inflammatory factor HMGB1 in SLE bone marrow microenvironment could promote the senescence of MSCs via TLR4/NF-κB signaling pathway, and inhibiting HMGB1 by EP could improve lupus nephritis and reverse the senescence signs of MSCs." (PMID 31303606, 2019).
meningococcal disease (14 papers, 2007 to 2022). "Genotype distribution of the CD14 C-159T and TLR4 Asp299Gly variants among patients with meningococcal disease compared to controls." (PMID 19809507, 2009). "Due to the low allele frequencies of rare variants, and findings reported for TLR4 in patients with meningococcal infection, we pooled all rare NSPs within each TLR and compared the frequencies of rare alleles between cases and controls in each ethnic group." (PMID 18091991, 2007). "In conclusion, we show that a significant proportion of meningococcal disease is caused by meningococci with underacylated lipid A. Possibly, due to inefficient stimulation of TLR4, lipid A variant meningococci poorly stimulate the inflammatory response and are better able to avoid clearance." (PMID 23209568, 2012). "The hypothesis that TLR4 plays an important role in the prevention of meningococcal disease corroborates with the finding that subjects with rare TLR4 mutations have an increased risk for developing the disease." (PMID 19390612, 2009). "In a cohort of children with invasive meningococcal infections TLR4 +896 was correlated with mortality, increased frequencies of ventilation support, application of inotropic substances, skin grafting, and limb loss." (PMID 23691182, 2013). "Broad stimulation of TLR4 in patients with invasive meningococcal disease leads to acute systemic inflammation followed by hypotension, circulatory collapse and shock." (PMID 23209568, 2012). "The major virulence factor in meningococcal disease is endotoxin consisting of lipopolysaccharide (LPS), a potent activator of the innate immune system via Toll-like receptor 4 (TLR4) in combination with co-receptors MD-2 and CD14." (PMID 23209568, 2012). "Moreover, depolymerization of the MT network disrupted intracellular TLR2 and TLR4 and inhibited IL-12 production in response to Neisseria meningitidis infection." (PMID 29184543, 2017). "In addition to meningococcal lipooligosaccharide (LOS), PBP2 may also be a relevant and direct player in host-pathogen interactions through TLR4 that influence the clinical outcome of meningococcal infection." (PMID 22046231, 2011). "We could not observe a significant influence of CD14 C-159T and TLR4 Asp299Gly polymorphisms on the risk of developing IMD in surviving meningococcal disease patients." (PMID 19809507, 2009).
migraine (14 papers, 2019 to 2025). "TLR-4 expression has been detected in the TG and nociceptive afferents of the trigeminal nerve, indicating the potential for LPS-induced changes in nociceptive signaling associated with migraine." (PMID 41465411, 2025). "To date, several studies have shown that TLR2, TLR3, and TLR4 are associated with migraine." (PMID 35987639, 2022). "Other evidence has indicated that TLR4 is associated with hyperalgesia in migraines." (PMID 35987639, 2022). "Earlier it was suggested that the 4 896 A > G polymorphism of the TLR-4 gene might be a risk factor for migraine." (PMID 34576297, 2021). "The physiological implications include energy production, the trigger of the inflammatory response through via TLR4 signaling pathway associated with pain pathogenesis, worsening pain, and a link to insulin resistance that is proposed to be a part of migraine pathophysiology." (PMID 34531722, 2021). "Our analyses revealed 283 genes, including some newly associated with migraine: MAML3, CELF4, IRX1, ASXL1, SPOCD1, CXCL, and TLR4." (PMID 41420111, 2025). "Although the relationship between TLR4 and migraine is more well-studied than that between TLR2 and TLR3, the related upstream and downstream mechanisms still require significant research." (PMID 35987639, 2022). "Although the involvement of TLR4 signalling in initiating and maintaining migraine-like behaviour in mice and inducing hyperalgesia in rats has been proposed, this is the first study that links the TLR pathway specifically to migraineurs." (PMID 36050647, 2022). "In periorbital hypersensitivity of migraine, the TLR4 antagonist (+)-naltrexone blocked the development of facial allodynia after supradural inflammatory soup." (PMID 35987639, 2022). "The TLR4 signaling was observed in initiating and maintaining migraine-like behavior through myeloid differentiation primary response gene 88 (MyD88) in the mouse." (PMID 34576297, 2021). "This study thus provides the firstevidence for involvement of TLR4 signaling through MyD88 in initiatingand maintaining migraine-like behavior and nucleus caudalis neuronalactivation in the mouse." (PMID 31342858, 2019). "We believe these convergent observations eachprovide substantial support for the role of TLR4 signaling in the malerelated to the migraine phenotype." (PMID 31342858, 2019). "A recent study showed that activation of TLR4/NF-κB also promotes migraine-related allodynia." (PMID 37190506, 2023). "Another study confirmed that the activation of the TLR4/NF–κB signalling pathway in the trigeminal system contributes to the development of hyperalgesia in a migraine rat model, and that the activation of microglia induced by dural inflammation is regulated by TLR4." (PMID 37190506, 2023). "Another study reported that TLR4 antagonists can inhibit microglial activation and the consequent releases of inflammatory mediators, and, similarly, block the development of allodynia after dural IS in migraine rats." (PMID 37190506, 2023). "Using a murine model of light aversionproduced by compound 48/80 (2 mg/kg, intraperitoneal) mast celldegranulation, employed as a surrogate marker for photophobia observedin migraineurs, we examined the role of TLR4 in migraine-like behaviorand neuronal activation." (PMID 31342858, 2019). "Therefore, TLR4 may play a role in the mechanism of migraine induced by FGIDS." (PMID 35987639, 2022). "Finally, we prioritized potential migraine drug targets, including losmapimod (which reduces production of toxic DUX4 protein) and TLR4 antagonists." (PMID 41420111, 2025). "This paralgesia state can be alleviated by TLR4 blockers (e.g., TAK-242), which also inhibit microglial activation and decrease the production of TLR4 downstream molecules and inflammatory cytokines in a rat model of migraine." (PMID 37190506, 2023). "Inhibiting TLR4 did not affect GABAARα1 expression, and improved migraine only." (PMID 36358363, 2022).
migraine (continued). "Surprisingly,female Tlr4−/− mice were no different thanthe WTs, suggesting that TLR4 may not be critical to48/80-mediated migraine-like behavior in females as in males." (PMID 31342858, 2019).
pulpitis (14 papers, 2018 to 2026). Inflammation of the dental pulp. "Consistently, LPS from Porphyromonas gingivalis (Pg), a pathogen commonly associated with symptomatic pulpitis, can directly excite trigeminal ganglion neurons via transient receptor potentials (TRPs) sensitized by toll-like receptor 4 (TLR4), resulting in CGRP production." (PMID 36430624, 2022). "This study confirmed that the expression of TLR4 on the cell bodies of TG neurons significantly increased after pulpitis, which was accompanied by increased TNF-α expression and CGRP immunofluorescence intensity in the TG." (PMID 40531313, 2024). "At 24 h pulpitis induction, the number of TLR4-positive neurons significantly increased when compared with controls, reaching a peak at 72 h and lasting for four weeks." (PMID 40531313, 2024). "According to the inflammation regulation mechanism of DPC@NPs in pulpitis, fibroblast membrane-camouflaged nanoparticles exert an anti-inflammatory role by intervening in LPS-activated TLR4-related signaling pathways." (PMID 34785637, 2021). "Nonetheless, it was evident that both TLR2 and TLR4 were induced on the macrophages and dendritic-like cells at the early stage of pulpitis." (PMID 30631444, 2018). "However, in the Cur group, from 72 h up to four weeks after pulpitis induction, the number of TLR4 positive neurons in the TG significantly decreased when compared with the control group." (PMID 40531313, 2024). "TLR4 levels were considerably elevated in pulpitis patients’ peripheral blood mesenchymal cells (PBMCs) and pulp tissues, and were negatively correlated with miR-27a-3p levels in blood and pulp tissues, respectively.TLR4 has been identified as a direct miR-27a-3p target gene." (PMID 36890871, 2023). "TLR4 is widely reported to be highly expressed in DPCs during the development of pulpitis." (PMID 34605740, 2021). "Bacterial infection in pulpitis may activate necroptosis through the Toll-Like Receptor 4 (TLR4)-RIPK3 pathway, leading to the release of damage-associated molecular patterns (DAMPs) that disrupt immune homeostasis, while mitochondrial dysfunction-induced ROS further aggravates oxidative stress." (PMID 41142308, 2025). "Therefore, inhibiting TLR4 signaling might be an effective method for the treatment of pulpitis." (PMID 34605740, 2021). "HMGB1 inhibitors alleviate pulpitis by blocking its interaction with receptors such as RAGE and TLR4, leading to reduced pro-inflammatory cytokine production in a dose-dependent manner, as demonstrated by systemic intraperitoneal administration in animal studies." (PMID 41142308, 2025). "Thus, the TLR4/MyD88-mediated NF-κB and p38 MAP kinase pathways are considered to be crucial signaling axes in LPS-induced pulpitis." (PMID 34785637, 2021). "Coinciding with the increase in TLR4 we also observed an increase in Trpv1 mRNA expression at 24 hours post injury, similar to increased protein expression found in rats with pulp exposure or CFA-induced pulpitis models." (PMID 32066827, 2020). "Dental pulps with pulpitis suffer higher expressions of proinflammatory cytokines (IL-1α, IL-1β, IL-6, and TNF-α) and innate immune response (TLR2, TLR4) than pulps without pulpitis." (PMID 31695620, 2019). "After administering Cur by intraperitoneal injection, the expression levels of Toll-like receptor 4 (TLR4), CGRP, glial fibrillary acidic protein (GFAP), fractalkine (CX3CL1), Tumor necrosis factor (TNF-α), and other factors were examined in the TG of pulpitis-induced rats." (PMID 40531313, 2024).
airway hyperresponsiveness (13 papers, 2011 to 2024). "The results revealed that LPS and poly (I: C) elevated Rrs and Ers, implying that activation of both TLR3 and TLR4 causes airway hyperresponsiveness (AHR)." (PMID 39614276, 2024). "Starkhammar and colleagues showed that combined stimulation of TLR3 and TLR4 causes airway hyperresponsiveness which is increased during an ongoing allergic inflammation." (PMID 34394070, 2021). "TLR4-deficient animals were subsequently identified to be protected from ozone-induced airway hyperresponsiveness." (PMID 22073274, 2011). "TLR4 also mediates inflammation and airway hyperresponsiveness after O3 exposure, triggered by release of the endogenous sugar hyaluronan." (PMID 31989925, 2020). "O3 exposure is associated with increased morbidity and mortality in human patients with cardiopulmonary disease; furthermore, it is now understood that TLR4 mediates the development of inflammation and airway hyperresponsiveness (AHR) after O3 exposure." (PMID 31989925, 2020). "We further demonstrated that FCPs given to mice induce allergic airway disease, including airway hyperresponsiveness, again through TLR4." (PMID 32485866, 2020). "The present study strongly demonstrate the importance of the TLR4/NF-κB-dependent signaling cascade for the pathogenesis of airway hyperresponsiveness and inflammatory injury." (PMID 25875290, 2015). "In this study, we further investigated the role of TLR4 adaptors in ozone–induced airway hyperresponsiveness (AHR) and the direct response to hyaluronan fragments (HA)." (PMID 22073274, 2011). "Additionally, in a humanized mouse model, ATIs caused an exacerbation of intestinal and lung allergic inflammation, and of airway hyperresponsiveness in a TLR4-dependent manner by using an anti-human TLR4 blocking antibody." (PMID 37426425, 2023). "This study was aimed to explore whether Toll-like receptors 4 (TLR4) of airway smooth muscle cells (ASMCs) play a role in lipopolysaccharide (LPS)-induced airway hyperresponsiveness and potential mechanisms." (PMID 25875290, 2015). "The specific mechanism of hyaluronan fragments-induced airway hyperresponsiveness remains unknown, but we identify a central role of TLR4-MyD88-TIRAP." (PMID 22073274, 2011). "Dex may attenuate airway hyperresponsiveness by inhibiting the TLR4/NF-κB pathway in mice." (PMID 37484380, 2023).
atrophic gastritis (13 papers, 2011 to 2024). "Another Japanese investigation found that having the TLR4 + 3,725 C allele and the miR-146a rs2910164 G/G variant together improved the likelihood of severe gastric atrophy in H. pylori-infected Japanese participants." (PMID 39035439, 2024). "According to the findings of a Japanese investigation, the TLR4 + 3,725 G/C polymorphism was a risk factor for severe gastric atrophy in Japanese people who were seropositive for H. pylori." (PMID 39035439, 2024). "The GC or CC genotypes of TLR4 rs11536889 have been associated with severe gastric atrophy in Japanese subjects who are Helicobacter pylori seropositive." (PMID 28002812, 2017). "Their study found that GG genotype of rs2910164 and TLR4 + 3725 C allele increased the risk of severe gastric atrophy in Helicobacter pylori-infected Japanese population." (PMID 25983750, 2015). "Recently, a novel polymorphism in TLR4 gene 3725G>C (rs11536889) with functional relevance was identified and linked with severe gastric atrophy in Asian population." (PMID 21864388, 2011). "miR-365 was poorly expressed in GC and atrophic gastritis tissues and GC cell lines, while TLR4, CDX2 and IRF3 were overexpressed." (PMID 33292210, 2020). "Western blot analysis showed that TLR4 was highly expressed in GC tissue and atrophic gastritis gastric tissue compared with adjacent cancer tissues (p < 0.05)." (PMID 33292210, 2020). "Another study showed a combined effect of TLR4 3725G>C and miR-146a G>C gene polymorphisms for risk of gastric atrophy, but not for GC." (PMID 21864388, 2011). "miR-365, TLR4, CDX2 and IPF3 expression was determined in GC and atrophic gastritis tissues and cells." (PMID 33292210, 2020).